EME1 (essential meiotic structure-specific endonuclease 1)
Description:
Non-catalytic subunit of the structure-specific, heterodimeric DNA endonuclease MUS81-EME1 which is involved in the maintenance of genome stability. In the complex, EME1 is required for DNA cleavage, participating in DNA recognition and bending. MUS81-EME1 cleaves 3'-flaps and nicked Holliday junctions, and exhibit limited endonuclease activity with 5' flaps and nicked double-stranded DNAs. Active during prometaphase, MUS81-EME1 resolves mitotic recombination intermediates, including Holliday junctions, which form during homologous recombination.
Synonyms: FLJ31364; MMS4L; SLX2A
Tractability: Small molecule: a structure with a bound ligand is known. PROTAC: UniProt records ubiquitination sites on it; ubiquitination databases record sites on it.
Gene: Protein-coding gene on chromosome 17 (50,373,220 to 50,381,483, forward strand). Ensembl gene ENSG00000154920.
Subcellular location: Nucleus, nucleolus
Subcellular location (Human Protein Atlas): Nucleoplasm
Pathways (Reactome):
DNA Repair: Fanconi Anemia Pathway; Resolution of D-loop Structures through Holliday Junction Intermediates
Gene Ontology:
Molecular function: crossover junction DNA endonuclease activity; DNA binding; protein binding
Biological process: double-strand break repair; replication fork processing; resolution of mitotic recombination intermediates; response to intra-S DNA damage checkpoint signaling; telomere maintenance; mitotic intra-S DNA damage checkpoint signaling; resolution of meiotic recombination intermediates; DNA repair
Cellular component: endodeoxyribonuclease complex; Holliday junction resolvase complex; nuclear chromosome; nuclear replication fork; nucleoplasm; chromatin; heterochromatin; nucleolus; nucleus
Genetic constraint (gnomAD): Loss-of-function variants: 58 observed, 57.84 expected, observed/expected ratio (o/e) 1, 90% interval 0.81 to 1.25. The upper end of that interval is the gene's LOEUF score, 1.25, which puts it in group 5 of 6, group 1 being the genes least tolerant of losing a copy. Missense variants: 567 observed, 642.33 expected, observed/expected ratio (o/e) 0.88, 90% interval 0.82 to 0.95. Synonymous variants: 205 observed, 238.03 expected, observed/expected ratio (o/e) 0.86, 90% interval 0.77 to 0.97.
Homologues: Orthologues: chimpanzee EME1 (98% identical), macaque EME1 (92% identical), pig EME1 (77% identical), rabbit EME1 (71% identical), dog EME1 (71% identical), mouse Eme1 (70% identical), rat Eme1 (69% identical), guinea pig EME1 (67% identical), zebrafish eme1 (36% identical), tropical clawed frog eme1 (31% identical), Drosophila melanogaster mms4 (14% identical). Paralogues in human: EME2 (22% identical).
Diseases named in the same sentence as EME1 in open-access papers:
EME1 is named in the same sentence as 29 diseases in open-access papers, as found by Europe PMC text mining. Sharing a sentence is not in itself a finding about the gene and the disease. The quoted sentences say what the papers report.
Fanconi anemia (9 papers, 2014 to 2024). Fanconi anemia (FA) is a hereditary DNA repair disorder characterized by progressive pancytopenia with bone marrow failure, variable congenital malformations and predisposition to develop hematological or solid tumors. "Again, DNA repair and cell-cycle-related genes (e.g., Fanca, Brca1, Eme1, Cdc6, Cdc7, Chek1) are enriched (e.g., KEGG terms: Fanconi anemia pathway, homologous recombination, cell cycle, Base excision repair)." (PMID 28638111, 2017).
breast carcinoma (5 papers, 2021 to 2025). "EME1 Ile350Thr variant in Southern Chinese females is significantly associated with susceptibility and early onset of breast cancer and its overexpression is suggested to lead to cisplatin resistance." (PMID 33662042, 2021). "Furthermore, downregulation of EME1 was also observed when SETD1A was depleted from BRCA1-mutated HCC1937 breast cancer cells, or ATM-mutated H1395 lung cancer cells, suggesting that this represents a conserved mechanism in multiple cancer types." (PMID 39994444, 2025). "Interestingly, in most cases, EME1 expression did not correlate with increased/decreased patient survival, except in the case of BRCA1-deficient breast cancer, where low EME1 expression associated with a favourable prognosis, although these two factors had partially separable impacts on survival." (PMID 39994444, 2025). "The meta-analyses of publicly available datasets provided by the Gene Expression Profiling Interactive Analysis platform and the bc-GenExMiner platform revealed induced expression of EME1 in many tumor types as well as breast cancer." (PMID 35563522, 2022). "For example, miR-449a has been reported to target EME1 and downregulate BRCA2 and RAD51 in breast cancer, while miR-146 targets and/or downregulates FANCM and BRCA1 in cervical, gastric, and breast cancer cells." (PMID 41008855, 2025). "The expression of EME1 in TNBC was significantly higher compared to other breast cancer subtypes (non-TNBC)." (PMID 35563522, 2022).
colorectal cancer (3 papers, 2016 to 2021). A primary or metastatic malignant neoplasm that affects the colon or rectum. "Colorectal cancer cells deficient in the DNA damage repair protein EME1 have shown significantly increased radiosensitivity to ruthenium-arene complex treatment." (PMID 34830778, 2021). "Colorectal cancer cells deficient in DNA damage repair proteins, EME1 and MUS81, were significantly more sensitive to both agents." (PMID 26867983, 2016).
epithelial ovarian cancer (2 papers, 2017 to 2025). "In summary, we show that SETD1A loss renders ATM-deficient and BRCA1-mutated breast, lung, and ovarian cancer cells resistant to PARPi by restoring HR, and that this is partly driven by defective EME1 transcription." (PMID 39994444, 2025).
gastric cancer (2 papers, 2021 to 2024). A primary or metastatic malignant neoplasm involving the stomach. "In this study, bioinformatics analysis results showed that EME1 was highly expressed in gastric cancer tissues and was associated with poor prognosis of gastric cancer." (PMID 34719326, 2021). "Therapeutically, MYB mediated EME1 activation promoted tumorigenesis in a GC cell line, orthotopic xenograft gastric cancer model." (PMID 34719326, 2021). "RNAseq data in the level 3 HTSeq-FPKM format in the TCGA STAD (gastric cancer) project were used for EME1 co-expression analysis." (PMID 34719326, 2021). "Subsequently, Silencing EME1 in two gastric cancer cell lines decreased the expression of Akt, CCND1, and GSK3B as well as the phosphorylation levels of Akt, CCND1, and GSK3B." (PMID 34719326, 2021). "EME1 was found to be upregulated in both gastric cancer cells and clinically obtained tumors." (PMID 34719326, 2021). "DNA damage plays a key role in various biological processes involved in malignant disease, the role of the DNA damage repair gene EME1 (essential meiotic structure-specific endonuclease 1) in gastric cancer (GC) development is unknown." (PMID 34719326, 2021). "The relationship between EME1, Akt, and MYB in the regulation of gastric cancer was also studied." (PMID 34719326, 2021). "Further validation results revealed that the expression of EME1 increased both in gastric cancer cell lines, including AGS and MGC-803, as well as gastric cancer tissue, and that EME1 promoted the proliferation and metastasis of gastric cancer and inhibited apoptosis both in vitro and in vivo." (PMID 34719326, 2021).
lung carcinoma (2 papers, 2023 to 2025). "Indeed, in BRCA1- or ATM-mutated breast, ovarian and lung cancer lines, low EME1 levels associated with decreased Olaparib sensitivity, which was not the case in BRCA2-mutated or unaltered cells." (PMID 39994444, 2025). "Reconstitution of EME1 partially reversed the suppressive effects of FIBP knockdown on lung cancer cell growth and proliferation." (PMID 37564211, 2023). "We further showed that overexpression of exogenous STAT3 reversed the decrease in EME1 expression in FIBP-deficient lung cancer cells, indicating that FIBP upregulates EME1 in a STAT3-dependent manner." (PMID 37564211, 2023). "Among these genes, EME1 exhibited the greatest downregulation in FIBP-depleted lung cancer cells." (PMID 37564211, 2023). "Our work reveals that FIBP modulates the STAT3/EME1 axis to drive lung cancer progression and radioresistance, indicating that targeting FIBP may be a novel intervention strategy for lung adenocarcinoma radiotherapy." (PMID 37564211, 2023). "Moreover, FIBP-deficient lung cancer cells showed increases in γ-H2AX foci formation and the Olive tail moment, and these increases were partially reversed by overexpression of EME1." (PMID 37564211, 2023).
lymph node metastasis (2 papers, 2021 to 2022). "As lymph node metastasis (LNM) is an important prognostic predictor of GC outcomes and a major cause of GC deaths, we further investigated whether EME1 expression was associated with lymph node metastasis in GC." (PMID 34719326, 2021). "Additionally, EME1 levels were strongly associated with the differentiation level of GC and lymph node metastasis." (PMID 34719326, 2021).
angiosarcoma (1 paper, 2023). A malignant tumor arising from the endothelial cells of the blood vessels. "EME1, FANCA, RAD51, TP53BP1, RAD51C, RPA1, and XRCC2 exhibited alterations in more than half the cases of the angiosarcoma cohort." (PMID 36779660, 2023).
astrocytoma (1 paper, 2016). "Furthermore, polymorphisms in CHAF1A and XRCC1 are associated with the risk of astrocytoma, whereas SNPs in EME1, ATM, GLTSCR1, and XRCC4 are associated with susceptibility to non-astrocytoma subtypes." (PMID 27613841, 2016).
bladder cancer (1 paper, 2022). "Our study found a substantial correlation between RAD51AP1, RAD54L, and EME1 gene expression and bladder cancer proliferation, Th2, and wound healing scores." (PMID 35559013, 2022). "The expression levels of EME1, RAD51, RAD51AP1, and RAD54L genes were significantly higher in high grade bladder cancer and invasive bladder cancer (p < 0.05) than in low grade bladder cancer and superficial bladder cancer." (PMID 35559013, 2022).
Bloom syndrome (1 paper, 2025). Bloom syndrome (BSyn) is a rare chromosomal breakage syndrome characterized by a marked genetic instability associated with pre- and postnatal growth retardation, facial sun-sensitive telangiectatic erythema, increased susceptibility to infections, and predisposition to cancer. "Elevated expression of KLF5 promotes the expression of key HRR pathway genes, including RAD51, checkpoint kinase 1 (CHEK1), RAD54 like (RAD54L), essential meiotic structure-specific endonuclease 1 (EME1), and Bloom syndrome (BLM), thereby reversing the HRR suppression mediated by PARPi." (PMID 40032852, 2025).
COVID-19 (1 paper, 2024). A disease caused by infection with severe acute respiratory syndrome coronavirus 2. "ACE (AUC: 0.923), CYP1A1 (AUC: 0.902), EME1 (AUC: 0.977), CD52 (AUC: 0.970), MYBL2 (AUC: 0.995), CDC25A (AUC: 0.998), BCL6 (AUC: 0.966) and CD3D (AUC: 0.955) showed relatively good diagnostic efficiency in distinguishing COVID-19 patients from healthy controls." (PMID 38978778, 2024). "The role of the remaining eight key genes (ALDH1L, EME1, PYGL, NNMT, PHGDH, CD52, CD3D, and ESM1) in COVID-19 and sarcopenia has been less studied, emphasizing their importance in future research." (PMID 38978778, 2024).
esophageal adenocarcinoma (1 paper, 2021). A malignant tumor with glandular differentiation arising predominantly from Barrett mucosa in the lower third of the esophagus. "Their results showed that EME1 is associated with reduced OS, indicating that EME1 is a prognostic biomarker in esophageal adenocarcinoma." (PMID 34719326, 2021).
gastric tumor (1 paper, 2022). "Through IHC analysis, we found in gastric tumor tissues (n = 10) that the protein expression of most of the genes in the DRGS, except for PARPBP, EME1, and RAD54L, was significantly increased." (PMID 35676932, 2022).
lung adenocarcinoma (1 paper, 2023). A carcinoma that arises from the lung and is characterized by the presence of malignant glandular epithelial cells. "To determine whether EME1 is an effector of FIBP in lung adenocarcinoma, we transfected the EME1 plasmid into FIBP-deficient H1299 cells." (PMID 37564211, 2023). "Taken together, these findings demonstrate that FIBP is a novel positive regulator of STAT3 and controls STAT3-dependent EME1 expression in lung adenocarcinoma." (PMID 37564211, 2023). "Accordingly, these results suggest that FIBP binds to STAT3 to enhance its transcriptional activity, thereby inducing EME1 expression in lung adenocarcinoma cells." (PMID 37564211, 2023). "Our data demonstrated that the observed effects induced by FIBP silencing were reversed at least partially by ectopic expression of EME1, implying that EME1 also participates in the biological function of lung adenocarcinoma." (PMID 37564211, 2023). "Overexpression of STAT3 partially reversed the decrease in the mRNA and protein levels of EME1 in FIBP-deficient lung adenocarcinoma cells, indicating that FIBP controls the expression of EME1 in a STAT3-dependent manner." (PMID 37564211, 2023). "Here, we revealed that FIBP associates with STAT3 to stimulate its transcriptional activity, which consequently induces the expression of EME1, thereby driving lung adenocarcinoma radioresistance." (PMID 37564211, 2023). "Importantly, we demonstrate that the biological effects of FIBP are partially dependent on EME1 in lung adenocarcinoma." (PMID 37564211, 2023). "Moreover, the effects induced by FIBP silencing are partially dependent on EME1 in lung adenocarcinoma." (PMID 37564211, 2023). "In summary, our research illustrates that FIBP interacts with STAT3 to increase its phosphorylation, thereby enhancing its transcriptional activity and inducing the expression of its target gene EME1, which ultimately contributes to lung adenocarcinoma progression and radioresistance." (PMID 37564211, 2023). "Notably, loss of FIBP also led to decreased protein levels of EME1 in two different lung adenocarcinoma cell lines, whereas overpression of FIBP increased the expression of EME1." (PMID 37564211, 2023).
nasopharyngeal carcinoma (1 paper, 2024). A carcinoma arising from the nasopharyngeal epithelium. "Three hub genes (EME1, WNT4, SHISA2) show strong correlation with m6A regulators and elevated levels of methylation modifications in nasopharyngeal carcinoma tissues." (PMID 39726587, 2024).
tumor (13 papers, 2013 to 2025). "By integrating transcriptome sequencing data, 19 m6A-modified genes were found to be upregulated in tumor tissues, leading to the development of a three-gene (EME1, WNT4, SHISA2) risk prognosis model." (PMID 39726587, 2024). "The study found RAD51AP1, RAD54L, and EME1 to be hub genes in HR patterns associated with immunotherapy response and tumor progression." (PMID 35559013, 2022). "The relationship between the abundance of tumour-infiltrating lymphocytes (TILs) and the expression of EME1/HNRNPAB/PLAUR/SEMA3A in pan-cancer and LUAD was demonstrated on heatmaps and lollipop graphs." (PMID 36091160, 2022). "Tumor weights on the last day of study were clearly reduced after transfection with sh-EME1, compared to that in the NC group." (PMID 34719326, 2021). "Additionally, the effect of EME1 on Ki-67 expression in transplanted tumor tissues was examined via immunohistochemistry." (PMID 34719326, 2021). "The expression analysis of EME1 in GC cases suggested that high EME1 levels in GC may promote tumor formation by enhancing cell proliferation and metastasis." (PMID 34719326, 2021). "Elevated EME1 expressions may enhance the proliferative and metastatic abilities of GC cells, thereby acting as a tumor-promoting factor via Akt." (PMID 34719326, 2021). "Our results reveal the potential role of EME1 in GC development and its molecular mechanism in tumor progression while suggesting that EME1 may be a potential therapeutic target for GC." (PMID 34719326, 2021). "Because this regulation frequently occurs in the EME1 promoter, we hypothesized that certain tumor-specific cytokines may specifically bind to the EME1 promoter and thus upregulate EME1." (PMID 34719326, 2021). "During this process, the DNA endonuclease MUS81/EME1 complex and PARP-dependent DNA repair pathways mediate shedding and cytosolic accumulation of genomic tumor DNA." (PMID 38912586, 2024). "The expression of LINC00460/EME1/HNRNPAB/PLAUR and SEMA3A was higher in most tumour tissues, including LUAD, than in the corresponding control tissues (P < 0.001)." (PMID 36091160, 2022). "Furthermore, we analyzed the expression of ceRNAs in tumour and control samples using TCGA, GTEx, and CPTAC databases and found that the expressions of LINC00460/EME1/HNRNPAB/PLAUR/SEMA3A were significantly higher in LUAD tissues." (PMID 36091160, 2022). "Additionally, we found support for the SL interaction between LIG1 and PARP1 and EME1 and PARP1 by analyzing the coexpression of LIG1, EME1, or FAAP24 and PARP1 in relation to the tumor, node, metastasis (TNM) stage of PCa samples (P value for LIG1-PARP1 < 0.001; P value for EME1-PARP1 < 0.05)." (PMID 39718835, 2024).
cancer (11 papers, 2013 to 2025). A tumor composed of atypical neoplastic, often pleomorphic cells that invade other tissues. "CCLE was used to assess the expression distribution of EME1/HNRNPAB/PLAUR/SEMA3A in pan-cancer cell lines." (PMID 36091160, 2022). "The GSCA database was used to examine the role of EME1/HNRNPAB/PLAUR/SEMA3A in 10 cancer pathways and found that EME1 was mainly involved in the activation of apoptosis, cell cycle and DNA damage response and inhibition of RAS/MAPK pathways." (PMID 36091160, 2022). "Several cancer-associated genes have been identified on chromosome 17q, including PPM1D, EME1, BRCA1, ERBB2, NF1, RAD51C, BRIP1 and BIRC5." (PMID 34885154, 2021). "This chromosomal region contains several genes connected to cancers including EME1, BRCA1, ERBB2, NF1, RAD51C, BRIP1, BIRC5 and PPM1D." (PMID 34885154, 2021). "Seven genes (BORA, DIS3, POLR2C, FAM175A, EME1, RNF139 and SHMT1) are considered potential biomarkers and/or potential targets for radiotherapy and chemotherapy, as well as cancer susceptibility, cancer progression and metastasis-related genes." (PMID 26517092, 2015). "Other notable genes that were significant in a specific cancer type included EME1 in KIRC and FANCM in BRCA." (PMID 26689913, 2015). "Given that SETD1A promotes EME1 transcription in vitro, and that this correlation was observed in cancer genomic datasets, we hypothesised that EME1 downregulation might drive the PARPi resistance observed in the absence of SETD1A." (PMID 39994444, 2025). "Moreover, loss/perturbation of EME1 phenocopies SETD1A loss in the absence of both BRCA1 and ATM and led to the restoration of HR, which was supported by data from cancer cell lines." (PMID 39994444, 2025).
EME1 also shares sentences with these, for which no sentence is quoted: alcoholic liver diseases (1 paper); cervical carcinoma (1); colon cancer (1); Fanconi anemia complementation group I (1); infection (1); lung squamous cell carcinoma (1); ovarian cancer (1); prostate carcinoma (1); sarcoma (1); sarcopenia (1); uterine cancer (1).